IL1B (interleukin 1 beta)
Diseases named in the same sentence as IL1B in open-access papers (continued):
Sharing a sentence is not in itself a finding about the gene and the disease.
respiratory distress syndrome (6 papers, 2014 to 2023). "Particularly, IL-1β upregulates the acute inflammatory response in respiratory distress syndrome by promoting the secretion of inflammatory cytokines from epithelial cells." (PMID 34818666, 2022). "IL-8 gene is greatly stimulated by IL-1β, but not by interferon and is elevated in respiratory distress syndrome in humans." (PMID 31412766, 2019).
retinal (6 papers, 2015 to 2025). "Compared with the WT group, the caspase-11−/− group showed significantly lower retinal IL-1β expression at both 16 and 24 h after retinal IR injury (both p < 0.05)." (PMID 39333859, 2024). "Retinal IL-1β expression was not significantly changed at 4, 8, 16, 24, and 48 h after retinal IR injury in the caspase-11−/− group." (PMID 39333859, 2024). "The mean concentrations for HCMV viral load, TNFα and IL1β were significantly reduced in case of patients with end organ retinitis (HR), whereas the mean concentrations of TGFβ and CXCL10 were significantly higher in case of patients with retinitis." (PMID 35538132, 2022). "HMGB1 led to the activation of canonical NLRP3 and non-canonical caspase-8 inflammasomes and the processing of IL-1β in retinal IR injury." (PMID 26224068, 2015). "First, endogenous arginase 1 (A1) but not A2 limits the induction of IL-1β in retinal macrophages after IR injury in vivo as a possible mechanism of protection; this finding complements our earlier observation that A1 also limits expression of TNF-α in retinal IR injury." (PMID 37735154, 2023).
rhinitis (6 papers, 2012 to 2025). An inflammation of the mucous membrane lining the nose, usually associated with nasal discharge. "IL-1β, encoded by IL1B, acts as a key amplifying factor linking microbial metabolic dysregulation to the inflammation of chronic rhinitis." (PMID 41395465, 2025). "iNOS is a major producer of NO and plays vital roles in patients with inflammatory diseases, including AD, rhinitis, and pollinosis, when it is stimulated by bacterial lipopolysaccharides or various cytokines, such as IL-1β, IL-2, and TNF-α." (PMID 29088069, 2017).
rotator cuff tears (6 papers, 2019 to 2025). "This partially contradicts the findings of others, showing a rather increased expression of pro-inflammatory factors like SDF1, IL-1β, TNF-α or IL-6 in the bursae of patients with a rotator cuff tear or frozen shoulders." (PMID 38201221, 2023). "Likewise, clinical specimens from patients with rotator cuff tears exhibit upregulation of TNF-α, IL-1β, and IL-6 in the subacromial bursa, implicating these cytokines in pain generation and chronic inflammation inflammatory cytokine." (PMID 40728980, 2025). "The authors found significantly elevated levels of IL-1β, IL-6, tumor necrosis factor (TNF-α), inducible nitric oxide synthase (iNOS), cyclooxygenase-2 (COX-2), and vascular endothelial growth factor (VEGF) in synovial tissue of shoulders with full-thickness rotator cuff tears." (PMID 32821573, 2020).
salmonellosis (6 papers, 2012 to 2024). Infections with bacteria of the genus salmonella. "Pro-inflammatory cytokines like TNFα and IL-1β, and anti-inflammatory IL-10 play an important role in the pathophysiological processes occurring in porcine salmonellosis caused by S. Choleraesuis." (PMID 35436975, 2022). "IL-1β and IL-18 are primarily responsible for triggering the intestinal inflammatory response characteristic of salmonellosis." (PMID 35338975, 2022). "Moreover, our findings identify the intersection of IL-1β signaling and the complement system as key host factors involved in controlling mortality during invasive Salmonellosis." (PMID 38236896, 2024). "Potential immunomodulating treatment strategies for invasive Salmonellosis could target the pathogen directly (e.g., based on drugs targeting T3SS or flagella) or target key host response proteins (e.g., TLR4, NLRC4, or IL-1β) depending on the phase of the immune response." (PMID 23055923, 2012). "The higher upregulation of pro-inflammatory genes (Ifnγ, Kc, Inos, Il1β) and the higher concentration of immune proteins (MPO, KC) that we observed in SA+/ST−/mCRAMP−/− and SA+/ST+/mCRAMP−/− mice are clear indications of a higher susceptibility to salmonellosis when cathelicidin is absent." (PMID 33292444, 2020).
Schnitzler syndrome (6 papers, 2014 to 2024). A rare, underdiagnosed disorder in adults characterized by recurrent febrile rash, bone and/or joint pain, enlarged lymph nodes, fatigue, a monoclonal IgM component, leukocytosis and systemic inflammatory response. "So far, the pathogenic background of Schnitzler`s syndrome with its enigmatic interplay between monoclonal gammopathy and increased IL-1β secretion by monocytes and macrophages has remained elusive." (PMID 37063861, 2023). "Our observation illustrates the long-lasting sustained positive effect of canakinumab for over 10 years in a patient with Schnitzler syndrome, confirming the key role of blocking IL-1β in the disease management." (PMID 37007766, 2023). "In patients with Schnitzler’s syndrome, in whom NLRP3 somatic mosaicism has been anecdotally identified, IL-1β secretion is up-regulated." (PMID 37007766, 2023). "However, a fast response to IL-1β blocking drugs may not be specific for Schnitzler’s syndrome or Schnitzler-like syndromes." (PMID 37063861, 2023).
scleroderma (6 papers, 2013 to 2023). Scleroderma is a rare autoimmune connective tissue disorder characterized by abnormal hardening of the skin and, sometimes, other organs. "The NLRP3 inflammasome and IL-1β are essential for scleroderma pathogenesis." (PMID 35396386, 2022). "Interestingly, we found that the expression of GSDMD, caspase-1, IL-1β, and IL-18 increased significantly at the early stage (days 7 and 14) of the disease in scleroderma mice." (PMID 35396386, 2022). "Moreover, the protein levels of cleaved-GSDMD, cleaved caspase-1 and mature IL-1β were also elevated in scleroderma mice." (PMID 35396386, 2022). "ELISA test of the tissue supernatant found that the level of IL-1β in the skin of the BLM treated group was increased, which further proved the existence of GSDMD-related pyroptosis in scleroderma mice." (PMID 35396386, 2022). "The results of RNA-seq also showed that the expressions of cytokines IL-1β and OSM and the key transcription factor IRF7 in scleroderma were down-regulated in GSDMD KO mice." (PMID 35396386, 2022). "Nimbolide attenuated the progression of scleroderma by controlling inflammatory factors such as TNF-α, IL-1β, and p-NF-κB and by downregulating the TGF-β/Smad signaling axis (inhibition of TGF-β expression and Smad2/3 protein phosphorylation)." (PMID 34258301, 2021). "Th17 cells and pro-inflammatory cytokines such as IL-1β, IL-6, IL-17, and TNF-α play important roles in the pathogenesis of scleroderma." (PMID 33947424, 2021). "From our results of RNA-seq and RT-qPCR, Western Blot and ELISA, we can make reasonable assumptions that BLM activates GSDMD and promotes the upregulation and secretion of IL-1β, while genetic ablation of GSDMD reduces the expression of IL-1β in BLM-induced scleroderma mice." (PMID 35396386, 2022). "Nevertheless, the role of pyroptosis executor gasdermin D(GSDMD), which is a downstream molecule of NLRP3 and is required for IL-1β release in some situations, has not yet been well elucidated in scleroderma." (PMID 35396386, 2022).
skin abscess (6 papers, 2015 to 2024). "Subsequently, pro-inflammatory cytokines such as IL-1β are released and these molecules promote an influx of neutrophils to the site of infection and play a distinct role in skin abscess formation." (PMID 25719526, 2015). "Interestingly, the inhibition of IL-10 during the vaccination process also led to a substantial increase in production of IL-1β within the skin abscess." (PMID 38973612, 2024). "S. aureus-induced IL-1β production by neutrophils is TLR2 dependent and known to be crucial for skin abscess formation." (PMID 33785850, 2021).
syphilis (6 papers, 2017 to 2022). A contagious bacterial infection caused by the spirochete Treponema pallidum. "In this study, we investigate the expression of the NLRP3 inflammasome during the development of tissue inflammation associated with syphilis, the activation of the inflammasome and release of IL-1β were estimated during T. pallidum infection in a rabbit model." (PMID 29490620, 2018). "In this study, we first demonstrated that miR‐223‐3p expression levels were decreased in syphilis patients when compared to healthy control, which was negatively correlated with caspase‐1 activation and IL‐1β expression." (PMID 33145937, 2020). "Most importantly, a notable negative correlation was observed between miR‐223‐3p and NLRP3, caspase‐1, and IL‐1β, respectively, in the serum of syphilis patients and healthy controls." (PMID 33145937, 2020). "Our study first identified dramatically decreased miR-216a-5p in plasma of syphilis patients compared with the healthy control, which was negatively correlated with the expression of inflammatory cytokines, including IL-1β, IL-6, and TNF-α." (PMID 31358689, 2019). "In the present study, we first identified that miR-216a-5p decreased in the plasma of patients with syphilis compared with the healthy control, which was negatively correlated with levels of inflammatory cytokines such as IL-1β, IL-6, and TNF-α." (PMID 31358689, 2019). "We have found that miR‐223‐3p induced a strong inhibition of T pallidum‐induced caspase‐1 activation and IL‐1β production, which indicates that it might be a potential therapeutic target for syphilis." (PMID 33145937, 2020). "We prospectively recruited all patients with a new diagnosis of syphilis and tested their plasma for IFNα, IFNγ, IL-1β, IL-12p40, IL-12p70, IP-10, MCP-1, MIP-1α, MIP-1β, IL-4, IL-5, IL-6, IL-7, IL-8, IL-10 and IL-17A at baseline pre-treatment and 6 months following therapy." (PMID 28143443, 2017). "A study found that the levels of IL-1β, IL-6, and TNF-α were elevated in serum collected from syphilis patients." (PMID 33282751, 2020). "The results showed that the miR-216a-5p expression level was negatively correlated with the expression of inflammatory cytokines IL-1β, IL-6, and TNF-α, indicating the potential function of miR-216a-5p in syphilis progression." (PMID 31358689, 2019). "In accordance with previous studies, the inflammatory cytokines IL-1β, IL-6, and TNF-α were found to be significantly up-regulated in plasma of syphilis patients compared with the healthy controls." (PMID 31358689, 2019). "Moreover, there was a negative correlation between the levels of miR-216a-5p and inflammatory cytokines such as IL-1β, IL-6, and TNF-α, which were dramatically increased in syphilis patients." (PMID 31358689, 2019).
thoracic aortic aneurysm (6 papers, 2019 to 2025). An aneurysm formed in the wall of the proximal portion of the descending aorta proceeding from the arch of the aorta. "Inhibition of IL-1β through genetic and pharmacological strategies decreased formation and enlargement of thoracic aortic aneurysms, suggesting that IL-1β may be a potential target for thoracic aortic aneurysm treatment." (PMID 30808715, 2019). "SIRT6 can bind to the IL-1β promoter and repress IL-1β expression, partly by reducing H3K9 and H3K56 acetylation and inhibiting inflammation and senescence in thoracic aortic aneurysms." (PMID 39372420, 2024).
thymoma (6 papers, 2010 to 2022). A neoplasm arising from the epithelial cells of the thymus. "To evaluate the possible association of increased CRP serum concentrations with proinflammatory cytokines we measured IL-6 and IL-1β serum concentrations in 39 patients with TETs (thymoma: n = 23; TC: n = 15) in comparison to age- and sex-matched volunteers." (PMID 28514756, 2017). "Sera from patients with APECED or thymomas and healthy controls were tested for autoantibodies against IL‐6, IL‐1β, IL‐21, IL‐23 (p19 + p40), or TGF‐β3 using LIPS assays that preserve the natural cytokine conformations." (PMID 27957331, 2016). "Compound 4a inhibited IL-1β-induced phosphorylation of the mitogen-activated protein kinase p38 in EL4 thymoma cells and in freshly isolated murine lymphocytes, and significantly attenuated IL-1β-induced fever response in vivo." (PMID 20981241, 2010). "The effects of IL-1β blockade are due to CD8+ T cells and seem to be improved in the murine EL-4 thymoma model, using anti-PD-1 Ab." (PMID 33261061, 2020). "Luciferase immunoprecipitation (LIPS) was used to screen for autoantibodies to IL‐6, IL‐1β, TGF‐β3, IL‐21, and IL‐23 in patients with APECED or thymoma." (PMID 27957331, 2016). "These authors identified eight cytokines that were significantly changed among MG patients with thymoma (i.e., IL-4, IL-8, IL-15, eotaxin, macrophage inflammatory protein-1α, macrophage inflammatory protein-1β, VEGF and IL-1b)." (PMID 25889429, 2015).
trachoma (6 papers, 2008 to 2020). "Recent evidence showed that IL-1β expression was weakly associated with progressive scarring trachoma and strongly associated with inflammatory episodes." (PMID 27249027, 2016). "Similarly, this immunosuppressive polarized environment was mirrored in infected TS cases where conjunctival IFNγ, TNFα, and IL-12 mRNA expression levels were decreased compared to levels among TF/TI cases, although IL-1β and TGFβ1 levels were consistently elevated for all grades of trachoma." (PMID 18628987, 2008). "We found that proinflammatory cytokines IL-1β (r = 0.259, P = 0.001) and TNFα (r = 0.168, P<0.05) were significantly associated with trachomatous disease and concurrent C. trachomatis infection compared with age and sex matched controls from the same region who did not have trachoma." (PMID 18628987, 2008). "Immunohistochemistry (IHC) studies using tissue from a small number of individuals with active trachoma have shown that MMP9, CTGF, platelet derived growth factor (PDGF) and IL-1β were up-regulated in infiltrating monocytes/macrophages and that IL-1β was increased in the conjunctival epithelium." (PMID 27249027, 2016).
vaginal infection (6 papers, 2020 to 2026). "In this study, the inflammatory profile was assessed by measuring levels of four pro-inflammatory cytokines, IL-6, IL-1β, TNF-α, and IL-8, known to be associated with inflammatory processes linked to vaginal infections." (PMID 38337685, 2024). "This modulation is associated with a significant reduction in the secretion of three key pro-inflammatory cytokines, IL-6, IL-1α, and IL-1β, which are typically upregulated during C. albicans vaginal infection and contribute to the inflammatory milieu." (PMID 39770658, 2024). "Vaginal infection with C. albicans resulted in a strong inflammatory response, including elevated concentrations of proinflammatory cytokines IL-1β and CxCL-2 (a murine cytokine with similarities to human IL-8), as well as neutrophil infiltration." (PMID 38055800, 2023). "The second of these was assessed with a multi-analyte flow assay kit to determine the levels of IL-6, TNF-α, IL-1β, IL-10, IL-1α, IL-17a, MCP-1, and IFN-γ in the supernatant of cervical tissue homogenate of GrpE-immunized mice and control groups after vaginal infection." (PMID 32849509, 2020).
ventricular dilatation (6 papers, 2021 to 2025). "The SNP of IL1B rs16944 (G/A) was associated with a reduced risk of ventriculomegaly on MRI (OR = 0.46, 95% CI, 0.22–0.95; p = 0.03) and cUS (OR = 0.38, 95% CI, 0.0–0.93; p = 0.034)." (PMID 34578364, 2021). "In the current study, we noted that the SNP polymorphism of IL1B rs16944 was associated with the reduced risk of ventriculomegaly, proposing a protective role against CNS damage in cCMV." (PMID 34578364, 2021). "On the other hand, the SNP of IL1B rs16944 (G/A) was associated with more than a 50% reduction in risk of ventricular dilatation diagnosed by MRI or cUS." (PMID 34578364, 2021). "The SNP of IL1B rs16944 was associated with a decreased risk of ventriculomegaly (OR= 0.46, 95%CI, 0.22–0.95; p = 0.03) in the best fitted log-additive model." (PMID 34578364, 2021). "Infants carrying heterozygous (G/A) or homozygous for minor allele (A/A) genotype of IL1B rs16944 had a reduced risk of ventricular dilatation on cUS compared with those carrying homozygous for major allele (G/G) genotype (OR = 0.38, 95% CI, 0–0.93; p = 0.034) in the best fitted dominant model." (PMID 34578364, 2021). "Furthermore, at physiological concentrations, intracerebroventricular delivery of metHgb activates TLR4 homodimers or TLR4/2 heterodimers, promoting nuclear translocation of NF‐κB as well as secretion of TNFα and IL‐1β, and is sufficient to cause ventriculomegaly." (PMID 39450988, 2024).
viral pneumonia (6 papers, 2020 to 2025). Inflammation of the lung parenchyma that is caused by a viral infection. "NETosis aggravates virus-induced lung injury and is increased in viral pneumonia by regulating the Hippo pathway via the NLRP3/IL-1β axis." (PMID 40659620, 2025). "Patients with viral pneumonia showed increased NLRP3 and IL-1β expression in monocyte-derived macrophages compared to healthy controls." (PMID 40659620, 2025). "The Hippo pathway was activated in monocyte-macrophages from patients with viral pneumonia, and both NLRP3 and IL-1β proteins were highly expressed in these patients compared to those in healthy volunteers." (PMID 40659620, 2025). "The IL-1β levels were elevated in severe CAP patient's BAL fluid samples, possibly because this study enrolled both pneumococcal pneumonia and viral pneumonia patients." (PMID 33634060, 2020). "ELISA results showed that XCH treatment could decrease levels of BALF IL-6, IL-1β, and TNF-α in mice with viral pneumonia." (PMID 35865338, 2022). "Additionally, serum inflammatory cytokine levels, such as IL-1β, TNF-α, and GM-CSF, were higher in these patients than in healthy volunteers, suggesting that significant inflammation was observed in patients with viral pneumonia." (PMID 40659620, 2025). "Signature cytokine levels of IL-1β is an important factor activated during acute phase of viral pneumonia, as its level may not be significant obtained from large number of patients infected by varying bacterial or fungal species." (PMID 33634060, 2020).
Yersinia infection (6 papers, 2021 to 2024). "In support of this, priming of macrophages with LPS prior to high MOI Yersinia infection rescued IL-1β release." (PMID 33397971, 2021). "This regulatory loop that controls IL-1β production via PGE2 might be an important mechanism controlling the output of inflammasome activation in Yersinia infection." (PMID 34319170, 2021). "In cells lacking NLRP3, ASC or NLRC4, caspase-1 is activated and IL-1β and IL-18 are still secreted upon Yersinia infection, suggesting that other inflammasomes are involved." (PMID 39513865, 2024). "Similar to cell death, IL-1β release in response to high MOI Yersinia infection was independent of TNFR1." (PMID 33397971, 2021). "Interestingly, in the context of insufficient TRIF signaling, or when pro-inflammatory signaling is only partially inhibited, as is the case with low MOI Yersinia infection, signaling through TNFR1 seems to supplement TRIF-mediated cell death and IL-1β release." (PMID 33397971, 2021). "However, at 30 MOI, Yersinia infection failed to induce IL-1β release, likely due to complete inhibition of pro-IL-1β synthesis at higher MOI." (PMID 33397971, 2021).